SPMIP9 (sperm microtubule inner protein 9)
Description:
Microtubule inner protein (MIP) part of the dynein-decorated doublet microtubules (DMTs) in flagella axoneme.
Synonyms: C2orf51; TEX37; TSC21; FLJ25369
Tractability: No criterion of Open Targets' tractability assessment is met for any kind of drug.
Gene: Protein-coding gene on chromosome 2 (88,524,649 to 88,529,585, forward strand). Ensembl gene ENSG00000172073.
Subcellular location: Nucleus; Cytoplasm; Cytoplasm, cytoskeleton, flagellum axoneme
Subcellular location (Human Protein Atlas): Connecting piece; Cytosol; End piece; Mid piece; Principal piece
Gene Ontology:
Molecular function: protein binding
Biological process: flagellated sperm motility
Cellular component: cytoplasm; cytosol; nucleus; axonemal A tubule inner sheath; sperm flagellum
Genetic constraint (gnomAD): Loss-of-function variants: 6 observed, 8.38 expected, observed/expected ratio (o/e) 0.72, 90% interval 0.39 to 1.4. That is too few expected variants to judge how well the gene tolerates losing a copy. Missense variants: 233 observed, 238.67 expected, observed/expected ratio (o/e) 0.98, 90% interval 0.88 to 1.09. Synonymous variants: 97 observed, 95.37 expected, observed/expected ratio (o/e) 1.02, 90% interval 0.86 to 1.2.
Homologues: Orthologues: chimpanzee SPMIP9 (97% identical), macaque SPMIP9 (92% identical), rabbit SPMIP9 (77% identical), dog SPMIP9 (72% identical), mouse Spmip9 (70% identical), pig SPMIP9 (70% identical), guinea pig SPMIP9 (68% identical), rat Spmip9 (67% identical).
Diseases named in the same sentence as SPMIP9 in open-access papers:
SPMIP9 is named in the same sentence as 1 disease in open-access papers, as found by Europe PMC text mining. Sharing a sentence is not in itself a finding about the gene and the disease.
SPMIP9 shares sentences with these, for which no sentence is quoted: asthenozoospermia (1 paper).